RNU1-31P (RNA, U1 small nuclear 31, pseudogene)
Gene: Small nuclear RNA gene on chromosome 2 (236,210,373 to 236,210,548, reverse strand). Ensembl gene ENSG00000200745.
Homologues: Orthologues: chimpanzee U1 (96% identical), rabbit U1 (56% identical), zebrafish U1 (38% identical). Paralogues in human: RNU1-89P (73% identical), RNU1-1 (73% identical), RNU1-2 (73% identical), RNU1-27P (73% identical), RNU1-28P (73% identical), RNU1-3 (73% identical), RNU1-4 (73% identical), RNVU1-18 (73% identical), RNVU1-29 (73% identical), U1 (73% identical), RNU1-11P (72% identical), RNU1-78P (72% identical), and 132 more.